RRAD (RRAD, Ras related glycolysis inhibitor and calcium channel regulator)
Diseases named in the same sentence as RRAD in open-access papers (continued):
Sharing a sentence is not in itself a finding about the gene and the disease.
lymph node metastases (1 paper, 2024). "The results showed a similar tendency (r = −0.82, P < 0.01), and patients with lymph node metastases also showed lower expression of RRAD along with higher expression levels of GLUT3." (PMID 38811531, 2024). "Furthermore, a risk prediction model was built based on TCGA data, and the results indicated that high-risk patients with low expression of RRAD and high expression of GLUT3 simultaneously had a poorer prognosis and a higher rate of lymph node metastases." (PMID 38811531, 2024).
ovarian carcinoma (1 paper, 2023). A malignant neoplasm originating from the surface ovarian epithelium. "In ovarian cancer, RRAD hypermethylation is mediated by RasV12 oncogenic transformation." (PMID 36979412, 2023).
tumor (23 papers, 2012 to 2025). "High levels of E6 and E7 oncoproteins, especially from high-risk HPV types, can downregulate the tumor suppressor RRAD, thereby inducing the NF-κB pathway, which leads to an elevated expression of A3 enzymes and increased tumor mutations." (PMID 39764440, 2024). "For the transcriptional regulation of RRAD, some studies indicated that hypermethylation in RRAD promoter region is associated with reduced RRAD expression in tumor tissues and leading to poor prognosis." (PMID 38811531, 2024). "In addition, Ki-67 was also found to be highly expressed at the tumor margin, indicating increased metabolic rate and cellular proliferation associated with the lower expression of RRAD." (PMID 38811531, 2024). "Similarly, aberrant expression of RRAD has been linked to different tumors, with RRAD acting as a tumor suppressor or oncogene, depending on the cancer type." (PMID 37489459, 2023). "In addition, a nonsense mutation at C terminal (p.R263X) of RRAD gene was detected in both the primary tumor and CTCs." (PMID 34616428, 2021). "We also demonstrated that low Ras-related glycolysis inhibitor and calcium channel regulator (RRAD) expression in the tumor margin activated glucose metabolism." (PMID 38811531, 2024). "Among the DEGs, RRAD seemed to be correlated with energy metabolism, and the current research does not support a potential regulatory relationship or interaction between RRAD and other proteins in the DEGs of tumor margin." (PMID 38811531, 2024). "RRAD is found to play opposite roles as a tumor suppressor gene or oncogene in human cancers, depending on cancer and cell type." (PMID 36979412, 2023). "RRAD exhibits a novel form of bi-directional interaction with the nm23 that a putative tumor metastasis suppressor." (PMID 36979412, 2023). "Being regulated in various pathways, RRAD plays wide spectrum cellular activity including tumor cell division, motility, apoptosis, and energy metabolism by modulating tumor-related gene expression and interacting with multiple downstream effectors." (PMID 36979412, 2023). "Mounting evidence showed that RRAD is important for the progression and metastasis of tumor cells, which play opposite roles as an oncogene or tumor suppressor gene depending on cancer and cell type." (PMID 36979412, 2023). "GTP-binding protein RAD (RRAD) has been reported to be a tumor suppressor in NPC, where the high methylation of the promoter region in RRAD causes its low level of expression and inactivates its function." (PMID 33564686, 2021). "It is a tumor-suppressor gene and encodes a RAS-related glycolysis inhibitor and calcium channel regulator (RRAD), a small Ras-related GTPase that has been implicated in metabolic disease and several types of cancer." (PMID 34616428, 2021). "RRAD expression was also examined in patient-matched samples, and all tumor tissue, including PDC from ascites, harbored more RRAD overexpression than non-tumor tissue." (PMID 31857616, 2019). "In this study, we investigated the mechanism by which RRAD expression regulated tumor invasion and progression." (PMID 31857616, 2019). "Our previous study demonstrated that RRAD was frequently methylated in EBV-associated NPC, and it functioned as a tumor suppressor by inhibiting cell proliferation, colony formation, and migration in RRAD-overexpressing NPC cells." (PMID 28716111, 2017). "Furthermore, the low expression of RRAD in the tumor margin resulted in increased GLUT3, which is the basis of vigorous metabolism." (PMID 38811531, 2024). "The role of RRAD is not necessarily independent; the regulation and downstream targets of RRAD as a tumor suppressor gene may interact with each other." (PMID 36979412, 2023). "The role of RRAD is not necessarily independent; the regulation and downstream targets of RRAD as tumor suppressor gene may interact with each other." (PMID 36979412, 2023).
tumor (continued). "High expression of FOSB+, NEAT1+, or XIST+ tumor cell-associated genes such as FSTL3, VTN, PAPPA, CCN1, RRAD, and GPRIN3 may predict poor survival in patients with LUSC, suggesting that these genes act as prognosis biomarkers." (PMID 37430270, 2023). "Therefore, both SHKBP1 and RRAD probably contributed to tumor development and drug resistance through RTK/RAS-related regulations." (PMID 34616428, 2021). "A total of 31 cancer cell lines (17 GC cell lines, 14 CRC cell lines), 59 patient-derived cells (PDCs from 48 GC patients and 11 CRC patients), and 84 matched pairs of primary cancer tissue and non-tumor tissue were used to evaluate the role of RRAD in vitro and in vivo." (PMID 31857616, 2019). "Furthermore, we chose several EZH2 or LSD1 potential targets (P15, P21, LATS1, LATS2, RND1, KLF2, E-cadherin, PTEN, ASPP2 and RRAD) with tumor-suppressor function, and hypothesized that they may involve in the contributions of AGAP2-AS1 to NSCLC progression." (PMID 27195672, 2016). "The bar graphs indicated that the expression profiles of ATF3, CXCL2, RRAD, AREG, and CXCL8 in the C0 subtype were expressed at greater levels than in the remaining tumor cell subtypes." (PMID 40936936, 2025). "In our investigation, we examined the expression of genes connected to stemness in the different tumor cell subtypes and determined that the expression levels of ATF3, CXCL2, RRAD, AREG, and CXCL8 were significantly higher in the C0 subtype." (PMID 40936936, 2025). "The link between RRAD and GLUT3 provides new insight into the tumor development mechanism and indicates that oral inhibitors targeting glucose metabolism are promising therapeutics for OSCC." (PMID 38811531, 2024). "RRAD translocates GCIP to the cytoplasm and inhibit the tumor suppressor activity of GCIP, which ultimately increases Rb phosphorylation and upregulates cyclin D1." (PMID 36979412, 2023). "Platelet-Derived Growth Factor (PDGF), acting as vascular endothelial growth factor, plays a pivotal role in regulating tumor growth and metastasis by targeting malignant cells, vascular cells, and stromal cells, which enhances EGR1 binding to RRAD promoter." (PMID 36979412, 2023). "RRAD expression was frequently increased in GC and CRC cell lines, and siRNA/shRNA-mediated RRAD inhibition induced significant decline of tumor cell proliferation both in vitro and in vivo." (PMID 31857616, 2019). "In our study, RRAD was prominently expressed in ascites PDC lines from GC and CRC compared to tumor and non-tumor tissues." (PMID 31857616, 2019). "Here, we used spatial metabolomics and the spatial transcriptome to identify enhanced energy metabolism in the tumor margin of OSCC and identified that the downregulation of Ras-related glycolysis inhibitor and calcium channel regulator (RRAD) in tumor cells mediated this process." (PMID 38811531, 2024). "In SETD8 downregulated genes, we found that RRAD, a member of the RAS-related GTPase subfamily and also known as the RAS family diabetes-related gene, can inhibit tumour cell proliferation and migration and has been identified as a tumour suppressor gene in many tumours." (PMID 36934248, 2023). "RRAD was markedly overexpressed in PDC from malignant ascites of CRC and GC compared to non-tumor tissues or primary tumor tissues." (PMID 31857616, 2019). "In vitro analysis could not reflect the interaction between tumor cells and tumor microenvironment, so mice bearing tumors derived from GC cells and CRC cells were treated to determine the anti-tumor effect of RRAD inhibition in vivo." (PMID 31857616, 2019).
cancer (20 papers, 2012 to 2024). A tumor composed of atypical neoplastic, often pleomorphic cells that invade other tissues. "The increase in cancer cell viability caused by silencing the expression of the RRAD gene can be reversed by silencing the expression of the SETD8 gene." (PMID 36934248, 2023). "In cancer, RRAD has been implicated in numerous processes, including the regulation of glycolysis, proliferation, NF-κB signaling, and apoptosis." (PMID 32515734, 2020). "In contrast, our study showed that RRAD expression was associated with cancer invasion, migration, and angiogenesis." (PMID 31857616, 2019). "The results showed that the increase in lipid peroxidation levels in cancer cells caused by knockout of SETD8 could be reversed by silencing the expression of the RRAD gene." (PMID 36934248, 2023). "In our study, we demonstrated that peripheral cancer cells promoted energy status by decreasing the expression of RRAD." (PMID 38811531, 2024). "RRAD modulates cancer cells’ proliferation and motility by directly interacting with CaM, CaMKII, and β-tropomyosin." (PMID 36979412, 2023). "RRAD disturbs cancer cell migration through Rho signaling pathway by binding to 14-3-3 and ROCK (Rho-associated protein kinase), thus interfering in the abundance of pSer3-cofilin that is a regulator of actin dynamics in NSCLC cells." (PMID 36979412, 2023). "Generally, the current studies on intracellular function of RRAD have been limited to specific cancer type." (PMID 36979412, 2023). "As oncogene, RRAD participates in various molecular pathways and promotes cancer progression by facilitating cell proliferation and migration." (PMID 36979412, 2023). "The further studies are warranted to delineate the mechanisms of RRAD expression and cancer progression." (PMID 31857616, 2019). "Quantitative RT-PCR assay and western blot assay showed that RRAD was markedly overexpressed in malignant cells of ascites, and RRAD inhibition resulted in suppression of cancer cell proliferation and invasion in CRC and GC cell lines." (PMID 31857616, 2019). "Among the upregulated candidate genes, we confirmed promoter DNA hypermethylation of RRAD (RAS associated with diabetes) in biopsy specimens and cancer cell lines." (PMID 30340457, 2018). "This is consistent with the report that RRAD knockdown in human cancer cells results in nuclear translocation of Maid and premature senescence." (PMID 26107180, 2015). "Besides, RRAD interacts with CaM, CaMKII, and β-tropomyosin which can regulate the cytoskeletal organization and promote cancer cell proliferation and motility." (PMID 36979412, 2023). "The results showed that overexpression of the SETD8 gene increased the activity of cancer cells, which could be reversed by overexpression of the RRAD gene." (PMID 36934248, 2023). "The knockdown of RRAD diminished the survival of bortezomib-resistant cancer cells by inducing mitochondrial apoptosis via proapoptotic Noxa/Bcl-2 modulation, which might be caused by caspase activation." (PMID 36979412, 2023). "RRAD is epigenetic silenced in cancer by histone demethylation." (PMID 36979412, 2023). "In view of its pro-tumorigenic role in cancer, RRAD may serve as a promising target for therapeutic intervention." (PMID 36979412, 2023). "RRAD further inhibited transcription of EGR1 in cancer genesis." (PMID 36979412, 2023). "This review will discuss the dual identity of RRAD in specific cancer type, provides an overview of the regulation and downstream effectors of RRAD to offer valuable insights for readers, explore the intracellular role of RRAD in cancer, and give a reference for future mechanistic studies." (PMID 36979412, 2023). "Furthermore, RRAD knockdown in human cancer cells results in cell cycle arrest and premature senescence associated with nuclear translocation of Maid." (PMID 26107180, 2015).
cancer (continued). "Our study indicates that RRAD contributes to such context-specific phenotypes conferred by TGFβ signaling, which may help to explain extensive data that report opposing impacts of RRAD expression in a variety of cancer types." (PMID 32515734, 2020). "Overexpression of RRAD inhibits the GLUT1 translocation to the PM, which is an important mechanism of RRAD to repress the aerobic glycolysis in cancer cells." (PMID 36979412, 2023). "Additionally, RRAD in senescence may contribute to its role in cancer." (PMID 36979412, 2023). "Gene expression analysis across all three cancer types subsequently found a common increase in the expression of five genes (BCAR1, COL1A1, IGSF3, RRAD, and TFPI2), which may further inform biomarker study for identifying CTCs." (PMID 36980717, 2023). "There has been no systematic summary based on the dual role of RRAD in cancer genesis, which would allow them to roundly review the position, function, and mechanism of RRAD." (PMID 36979412, 2023). "However, owing to the nonspecific cytotoxicity (MI/TI) and efficacy (AH) against cancers, Lee, Yeom demonstrated that RRAD inhibition results from the hydrogen bonding between oxeladin and the Gln250 of RRAD, and the pi-pi stacking interactions of oxeladin with the Lys228 or Arg249 of RRAD." (PMID 36979412, 2023).
infection (6 papers, 2013 to 2023). The state of being infected such as from the introduction of a foreign agent such as serum, vaccine, antigenic substance or organism. "Two small GTPases, RASD1 and RRAD, were directly induced by the infection." (PMID 31653857, 2019). "To investigate the influence of RASD1 and RRAD on viral production, we depleted RASD1 and RRAD by small interfering RNA (siRNA) knockdown prior to infection, and observed increased virion production at 16 hpi, suggesting that both genes posses some antiviral activity." (PMID 31653857, 2019). "At every 24 hours within 4 days after lentiviruses infection of SiHa and CaSki, we used Q-PCR to analyze the expression of E6, E7, DNA methyltransferase genes (DNMT1, DNMT3A, DNMT3B and DNMT3L), and tumor suppressor genes (MT1G, NMES1, RRAD, SFRP1, SPARC and TFPI2)." (PMID 26329329, 2015).
metabolic disease (2 papers, 2018 to 2021). A congenital disorder (due to inherited enzyme abnormality) or acquired (due to failure of a metabolically important organ) disorder resulting from an abnormal metabolic process. "Putative candidate genes FAM96B (family with sequence similarity 96 member B) and RRAD (Ras related glycolysis inhibitor and calcium channel regulator) for these SNPs are associated with gastrointestinal and metabolic diseases, and with the development of the digestive system and disorder networks." (PMID 30463512, 2018).
cardiovascular disease (1 paper, 2013). "At 4 weeks post-MI, 4 genes (DOCK9, MBNL1, RRAD, and ZSWIM6) by all of 37 unique altered transcripts were related to cardiovascular disease." (PMID 23372767, 2013).
RRAD also shares sentences with these, for which no sentence is quoted: Fanconi anemia (5 papers); hepatocellular carcinoma (3); lymphoma (3); HCMV infection (2); heart failure (2); hypertrophic cardiomyopathy (2); leukemia (2); neuroblastoma (2); Ventricular arrhythmia (2); ataxia telangiectasia (1); atrioventricular block (1); Autoimmunity (1); cardiomyopathies (1); channelopathy (1); colorectal cancer (1); diabetic cardiomyopathy (1); dilated cardiomyopathy (1); heart disease (1); hepatitis C (1); hypertrophy (1); metabolic syndrome (1); myocardial infarction (1); non-small cell lung carcinoma (1); oral cancer (1); ovary cancer (1); pituitary adenomas (1).